NOX1 (NADPH oxidase 1)
Diseases named in the same sentence as NOX1 in open-access papers (continued):
Sharing a sentence is not in itself a finding about the gene and the disease.
colon carcinoma (continued). "Nox1 is also required for Ras-mediated VEGF expression in colon cancer cells and has been shown to be a key player in the angiogenic switch." (PMID 23071493, 2012). "Nox1 siRNA treated cells were then used to investigate the role of Nox1 in colon cancer cell adherence." (PMID 23071493, 2012). "TNF-α, a vital cytokine produced by the inflammatory response has previously been reported to increase transcription of Nox1 and increase superoxide production in colon cancer cells after 24 hours." (PMID 23071493, 2012). "This study shows that the potentiating effects of inflammation on tumour cell metastasis are derived from endogenous ROS, predominantly generated from Nox1 in colon cancer cells." (PMID 23071493, 2012). "This growth factor-ras-rac1-NOXA1 signaling pathway partially explains why colon tumor cells that harbor a mutant K-ras gene, or exhibit overexpression of growth factors and/or their receptors have constitutively activated NOX1 activity." (PMID 24392268, 2012). "This study demonstrates that both Nox1 and Nox2 expression increases synergistically in colon cancer cells to produce ROS following LPS treatment." (PMID 23071493, 2012). "The subunit Nox1 of NADPH oxidase is expressed in human colon cancer cells." (PMID 40722996, 2025). "GKT significantly prevented the protein and mRNA expression of COX2 and PGE2 production induced by IL1β, indicating that NOX1 expression and activity may be crucial for the expression of inflammatory markers in colon cancer cells." (PMID 39125413, 2024). "In colon cancer cells with a normal Wnt pathway, Nox1 mediates Wnt-induced cell growth, but not in APC-deficient colon cancer cells, which have constitutive Wnt signaling activity." (PMID 37443096, 2023). "NOX1 is also highly expressed in colon cancer cells and supports their proliferation." (PMID 35740948, 2022). "NOX1 may drive vascular complications in diabetes, such as diabetic retinopathy, and perpetuate the proliferation of colon cancer." (PMID 35740948, 2022). "Cell proliferation was mediated by NADPH Oxidase 1 (Nox1) expression in colon carcinoma cell lines." (PMID 34025929, 2021). "High expression of Nox1 in colon cancer accelerated the tumor growth and inhibition of Nox1 might become a new therapeutic strategy for colorectal cancer treatment." (PMID 34025929, 2021). "Thus, it is highly relevant that we have recently demonstrated NOX1 expression in human colon cancer cells to be dramatically up-regulated by a variety of the same pro-inflammatory molecules present in the colon cancer matrix." (PMID 34829628, 2021). "Therefore, we initiated a series of experiments focused on elucidating the functional extent of NOX1 in colon cancer cells following the elaboration of a validated human antibody targeting NOX1." (PMID 32428030, 2020). "As the human colon carcinoma HT-29 expresses Nox1 and generates ROS following PMA stimulation, we used HT-29 to test if our CL method could detect low concentrations of ROS in HT-29 cells." (PMID 31285782, 2019). "NOX1 is highly expressed in colon cancer cell lines and promotes proliferation." (PMID 31249132, 2019). "NOX1 is highly expressed in colon cancer and promotes tumor growth." (PMID 31249132, 2019). "Although this possibility must be acknowledged, it is also possible that the downstream phenotypic consequence of NOX1 knockdown could vary based on the relative expression of pro- or anti-apoptotic genes in human colon cancer cell lines." (PMID 28330872, 2017). "The first of the NOX2 homologues to be described, NOX1, was discovered through study of Caco2 human colon cancer cells; recent experiments have clarified the role of NOX1-mediated ROS production in colon cancer cell migration, integrin signaling, proliferation, and carcinogenesis." (PMID 28498822, 2017). "These experiments suggested that ROS generated by NOX1 might affect IL-4/IL-13-dependent signal transduction events in colon cancer." (PMID 28498822, 2017).
colon carcinoma (continued). "Furthermore, NOX1-dependent ROS enhance colon cancer proliferation by increasing cell cycle progression through S phase." (PMID 28498822, 2017). "Furthermore, transient knockdown of NOX1 can decrease proliferation of human HT-29 colon cancer cells." (PMID 28330872, 2017). "It has been reported that diphenyleneiodonium have therapeutic potential for NADPH oxidase-containing human colon cancers in vivo and that at least part of their antineoplastic mechanism of action may be related to targeting Nox1." (PMID 29020948, 2017). "To examine the relationship between exogenous IL-4 or IL-13 exposure and the expression of NOX1, we first determined whether the NOX1-expressing colon cancer cell lines under study possessed IL-4Rα, as has been reported previously." (PMID 28498822, 2017). "To examine the clinical relevance of our finding that in colon cancer cell lines IL-4 upregulates the expression of a functional NOX1-L isoform, we measured NOX1 expression in twenty tissue pairs consisting of surgically-resected colon cancers and their adjacent normal colonic mucosae." (PMID 28498822, 2017). "In human colon cancers, Nox1 is overexpressed and correlates with ROS–dependent cancer invasion." (PMID 25386960, 2014). "And Nox1 was measured to be expressed in colon cancer samples and cancer cell lines Caco2, HT29, and T84 and human melanoma cell lines, which may likely be able to facilitate cancer cell migration and invasion." (PMID 24669283, 2014). "Finally, we analyzed the distribution of Nox1 because of recent evidence that it is present in invadopodia and required for their formation in colon cancer cells and that Nox1 is regulated by Src and Tks5." (PMID 22873355, 2012). "Although a significant correlation between oncogenic RAS status and NOX1 mRNA levels could not be demonstrated in colon cancer cell lines, RAS mutational status did correlate with NOX1 expression in human colon cancer surgical specimens." (PMID 32428030, 2020). "We recently reported that stable knockdown of NOX1 in HT-29 colon cancer cells (clone 6A with > 90% inhibition of NOX1; and clone Si6/G6 with ≈ 65% NOX1 knockdown) significantly decreases ROS formation compared to cells carrying a scrambled NOX1 shRNA (SC cells) or the parental line." (PMID 28498822, 2017). "However, Nox1-generated ROS was found to mediate EGF-induced inhibition of the Rho activity in human colon cancer Caco2 cells that may be required for cell migration." (PMID 24669283, 2014). "Nox1 may represent a valuable target in which to prevent colon cancer metastasis." (PMID 23071493, 2012). "The effect of Cd-O2/N2 atomized gas on the expression levels of NOX1, SOD2, and CAT in the colon tumors of the CC mice with intestinal stents implanted in them was not statistically significant." (PMID 38535948, 2024). "In vivo, inhibition of host NOX1 blocks CRC tumor growth, and small hairpin RNA-mediated NOX1 silencing suppresses tumor growth in mouse models of colon cancer." (PMID 37516013, 2023). "It has been previously reported that NOX1 interacts with ADAM17 and protects it from ubiquitin-mediated degradation in human colon cancer cells." (PMID 38137406, 2023). "NF-κB is capable of inducing NOX1 expression and the generation of NOX-derived ROS is dependent on NF-kB activity in colon cancer cells." (PMID 36125689, 2023). "Another study looked at the effect of NOX1 inhibitor, GKT771, on mice with established colon carcinoma." (PMID 35741081, 2022). "It has been reported that NOX1 is an abnormal expression of NOX subunit in tumor cells, which plays a crucial role in cell proliferation, apoptosis, and cell migration of colon cancer, gastric cancer, skin cancer and melanoma." (PMID 35418176, 2022). "As expected, HT-29 human colon cancer cells produce more ROS at baseline than either SW620 or KM-12 cells, since only this cell line possesses a full complement of the NOX1 subunits that are required for oxidase activity." (PMID 34829628, 2021).
colon carcinoma (continued). "In support of the previous assumption, it has been shown that oncogenic KRAS promotes ROS generation in colon cancer cells (HCT116 KRASG13D and SW480 KRASG12V) through the signalling cascade p38/PDPK1/PKCδ/p47phox/NOX1." (PMID 33691728, 2021). "NOX1, NOX2, and NOX4 expression in cancer cells promotes tumor growth and metastasis in several cancers, including melanoma, gastric, pancreatic, and colon tumors." (PMID 31249132, 2019). "NADPH oxidase 1 (NOX1), a membrane-bound flavin dehydrogenase that generates O2 ̇̄, is highly expressed in colon cancer." (PMID 28330872, 2017). "Under basal conditions, less invasive human colon cancer cells (HT29 and Caco-2) showed low MMP-7 expression but high NOX1 expression and AMPK phosphorylation." (PMID 26116564, 2015). "However, it is unclear whether or not ROS-associated AMPK activation is related to NOX1, which is highly expressed in colon cancer cells compared to normal adjacent tissues." (PMID 26116564, 2015). "This LPS activated Nox mechanism facilitates a significant increase in SW480 colon cancer cell adhesion to collagen I, which is inhibited by DPI, Nox1 siRNA and a PI3K inhibitor." (PMID 23071493, 2012). "Similarly to IL1β, PGE2 also promoted ROS production and NOX1 and COX2 expression, which were inhibited when colon cancer cells were pre-treated with SW, CW, and BF, indicating that the bean extracts also inhibited the effects of exogenous PGE2." (PMID 39125413, 2024). "The implantation of intestinal stents inhibited the expression of Superoxide Dismutase 1 (SOD1) in the colon tumors of the CC mice, with no evident effects on the expression levels of NOX1, SOD2, and Catalase (CAT) enzymes." (PMID 38535948, 2024). "Another report has shown that treatment of colon cancer cells with WNT3A, a member of the WNT family, induces ROS production through the activation of NADPH oxidase 1 (NOX1), an enzyme responsible for the catalytic one-electron transfer of oxygen to generate superoxide or H2O2." (PMID 35453355, 2022). "The 80–90% knockdown of NOX1 expression using shRNA increased tumor cell doubling time two- to three-fold without increasing apoptosis in HT-29 human colon cancer cells." (PMID 35740948, 2022). "In order to confirm the baseline and PMA-dependent production of superoxide in HEK293 cells overexpressing NOX1, and in HT-29 and LS513 colon cancer cell lines, a widely used assay that relies on measuring the reduction of acetyl-cytochrome c was also employed." (PMID 32428030, 2020). "In LS513 colon cancer cells that endogenously express NOX1, the NOX1 band was also detected in lysate from the membrane fraction (left), and the intensity of the immunoreactive band was strongly attenuated in LS513 cells transfected with NOX1 siRNA (right)." (PMID 32428030, 2020). "A representative image from a moderately differentiated adenocarcinoma of the colon displayed non-uniform, strong cytoplasmic NOX1 protein staining in colon cancer epithelial cells." (PMID 32428030, 2020). "A colon carcinoma model was used because NOX1 is expressed at low level in normal colon epithelial cells and is highly up-regulated in colon adenocarcinoma, which, therefore, represents an ideal tumor target for colorectal cancer treatment." (PMID 31249132, 2019). "Nox1 (NADPH oxidase 1) was also reported to mediate the Ras-dependent up-regulation of VEGF expression and, angiogenesis via the Ras/ERK-dependent Sp1 phosphorylation and activation in CaCO-2 colon cancer cells." (PMID 31766246, 2019). "In human colon cancer cells, proteasomal degradation of NoxO1 reduces the Nox1-dependent ROS formation, and expression and stability of NoxO1 were significantly increased in human colon cancer tissues compared to normal colon." (PMID 29867954, 2018). "We were stimulated to pursue these investigations by the current lack of clarity regarding the role of NOX1 in colon cancer." (PMID 28330872, 2017).
colon carcinoma (continued). "Finally, NOX1, NOXO1, NOXA1, and p22phox expression are all significantly increased in colon cancers when compared with simultaneously resected, adjacent, histologically uninvolved colonic epithelium." (PMID 28330872, 2017). "Higher metastatic potential is correlated with elevated matrix metalloproteinase-7 (MMP-7) expression in human colon cancer cells; less invasive colon cancer cells, such as Caco2 and HT29 cell line, present low MMP-7 expression level and high NOX1 and AMPK phosphorylation levels." (PMID 28626501, 2017). "Moreover, in human colon cancer cell lines, lipopolysaccharide (LPS) treatment increases the expression levels of NOX1 and NOX2 expression, and NF-κB inhibitor attenuates the increase in NOX1 and NOX2 expression." (PMID 33757467, 2021). "In a previous study, we found that exposure of LS174T human colon cancer cells to DPI (250 nM) or DTI (10 μM) for 24 h produced a significant (>80%) inhibition of NOX1 mRNA expression without altering the expression levels of the antioxidant enzymes catalase or glutathione peroxidase." (PMID 34829628, 2021). "Importantly, tissue expression of NOX1 in colon carcinoma patients has no prognostic value regarding survival." (PMID 31249132, 2019). "When examined in resected tissues from patients with colon cancer, the authors found increased active NADPH oxidase 1 in the tumor tissue relative to the adjacent normal colon tissue, leading them to suggest that IL-4/IL-13-driven NADPH oxidase 1 expression may drive colon carcinogenesis." (PMID 29922293, 2018). "Stable genetic inhibition of NOX1 with shRNA significantly diminishes the proliferation of HT-29 cells that possess functional NOX1, but not of the HCT116 human colon cancer line that lacks an active NADPH oxidase." (PMID 34829628, 2021). "To confirm that the antitumor effect of GKT771 was not directly dependent on NOX1 expression in cancer cells, we studied the effect of GKT771 on the growth of DLD1 and LoVo cells, two human colon cancer cell lines expressing different levels of NOX1, grafted onto NSG mice." (PMID 31249132, 2019). "In colon cancer cells, this molecular switch from NOX1 to NOX2, together with NOX2-derived ROS, increases MMP-7 expression by the deactivation of AMPK, and the TPA-induced phenotype can be reverted by NOX2 but not NOX1-targeting siRNA, suggesting that NOX2 activity induces an invasive phenotype." (PMID 28626501, 2017).
diabetes (52 papers, 2011 to 2025). "They showed that deficiency of NOX1 reduces lesion size and ROS levels in the aorta in the presence of diabetes." (PMID 36225554, 2022). "NOX1, expressed in vascular smooth muscle tissue and endothelial cells, is apparently an important target in diabetes-associated atherosclerosis considering that its inhibition significantly reduces ROS production and vasculopathy." (PMID 32377289, 2020). "Induction of eNOS uncoupling comprises a significant source of ROS in diabetic animal models and impairs the ability to repair endothelial tissue damage, and NOX1 has been suggested as the predominant NOX isoform underlying the uncoupling of eNOS in diabetes." (PMID 31382355, 2019). "Although it seems clear that NOX1 contributes to diabetes-associated endothelial dysfunction, it is difficult to make assertions regarding the role of NOX1 in the control of glucose homeostasis." (PMID 31382355, 2019). "AGE/RAGE signaling has been implicated in oxidative stress associated with diabetes-mediated vascular calcification through activation of Nox-1, TGF-β mediated fibrosis, NFκB, and ERK1/2 pathways and decreased expression of SOD-1." (PMID 27547766, 2016). "Therefore, how precisely NOX1 expression in peripheral monocytes in humans is linked to cardiac disease and to diabetes still needs to be established." (PMID 34849611, 2022). "Nox4 has been implicated in renal injury in mouse models of diabetes, effects that are ameliorated with Nox1/4 inhibitors and in mice deficient in Nox4.54, 55 Nox5 may also be important in diabetes-associated vascular injury and nephropathy." (PMID 29459239, 2018). "Similarly, Nox1 deficiency reduced plaque accumulation in ApoE−/− mice treated with streptozotocin, a drug that induces type 1 diabetes mellitus." (PMID 29710840, 2018). "In Apoe+ mouse models with induced diabetes, either genetic deletion of Nox1 or pharmacological inhibition with GKT137831 (setanaxib, a dual NOX1/NOX4 inhibitor) result in a significant reduction in the atherosclerotic burden." (PMID 40725037, 2025). "This demonstrated that the activation of NF-κB-mediated NOX1 is an important process of OS in diabetes." (PMID 39064844, 2024). "AGE/RAGE signaling increases oxidative stress to promote diabetes-mediated vascular calcification through activation of Nox-1 and decreased expression of SOD-1." (PMID 36979367, 2023). "The interaction between AGE and RAGE stimulates NADPH oxidase-1 which contributes to reactive oxygen species production in diabetes." (PMID 35453469, 2022). "The interaction between AGE and the receptor for AGE (RAGE) stimulates NADPH oxidase-1 which contributes to reactive oxygen species production in diabetes." (PMID 35453469, 2022). "NOX1 expression is increased in the plaques of patients with cardiovascular events or diabetes, and deleting NOX1 reduces lesion area in both apolipoprotein E deficient (ApoE−/−) mice and in ApoE−/− mice after induction of diabetes." (PMID 36497101, 2022). "Studies have proven that NOX1 is a potential therapeutic target in diabetes mellitus-related vasculopathies." (PMID 36225554, 2022). "Taken together, the results indicated that the inhibition of NOX1 expression preserved diabetes-induced cardiac dysfunction." (PMID 36225554, 2022). "The importance of Nox1 in diabetic nephropathy, another end-stage disease of diabetes mellitus, has been demonstrated using a rodent model of genetic obesity." (PMID 34571964, 2021). "Excess ROS derived from Nox1 and Nox4 have been shown to contribute to diabetic retinopathy, an end-stage disease of diabetes mellitus, which threatens vision as a result of increased vascular permeability and neovascularisation." (PMID 34571964, 2021). "Its levels in atherosclerotic lesions of both humans and rabbits were shown to be extremely low, while overexpression of NOX1 was observed in patients with cardiovascular disease or diabetes mellitus." (PMID 32664404, 2020).